ESR1 (estrogen receptor 1)
Diseases named in the same sentence as ESR1 in open-access papers (continued):
Sharing a sentence is not in itself a finding about the gene and the disease.
endometriosis (continued). "These outcomes suggest that thymol functions as an estrogen antagonist in endometriosis treatment, likely by competitively binding to ESR1, thereby impeding the binding of E2 to the protein, and consequently obstructing the development of endometriosis." (PMID 39684860, 2024). "Genes involved in the initiation and regulation of autophagy (e.g., mTOR, CXCR4, and ESR1) are upregulated in endometriosis." (PMID 38645639, 2024). "Quantitative reverse transcription PCR was used to determine ESR1 gene expression in the eutopic endometrial tissue of the controls and endometriosis patients." (PMID 39200122, 2024). "For example, in the endometrium of women with endometriosis, the regulation of ESR1 expression during the menstrual cycle is disturbed with higher levels of receptor expression seen in the secretory phase, compared to controls." (PMID 39200122, 2024). "We compared our differentially methylated sites and only found consistent results on hyper-methylation on ESR1.Consistently, downregulation of ESR1 mRNA level in endometriosis was also reported in few studies." (PMID 38844959, 2024). "Studies in the baboon model of endometriosis have shown a time-dependent reduction in ESR1 within eutopic endometrial stromal cells a month after the induction of endometriosis." (PMID 38892003, 2024). "The results from this analysis showed a 2.6-fold increase in ESR1 mRNA levels (2.6 median increase; adjp = 0.0303) in the eutopic endometrium of women with endometriosis, compared to controls." (PMID 39200122, 2024). "At the same time, ESR1 showed low expression, and related studies suggested that ESR1 can affect the possibility of pregnancy in infertile patients with endometriosis." (PMID 36660246, 2023). "What's more, both AR and PGR were identified as the hub genes between normal endometria and those of endometriosis patients, and ESR1 was selected as the hub gene between eutopic and ectopic endometria from the same patients." (PMID 36860677, 2023). "ESR1 is an estrogen receptor and ligand-activated transcription factor that plays a key role in endometriosis." (PMID 36817586, 2023). "Hormonal treatments for endometriosis primarily target ESR1, ESR2, or PGR and have the highest affinity for these receptors; however, due to the structural similarity of hormone receptors, off-target effects at other receptors are possible." (PMID 37996888, 2023). "In patients with endometriosis, it was demonstrated that the increase in the expression of estrogen receptor (ESR1) occurred during implantation." (PMID 36135172, 2022). "A meta-analysis reported that genes associated with endometriosis that were involved in hormone signalling (WNT4/CDC42, GREB1, ESR1, FSHB) were also associated with diagnosis of fibroids." (PMID 35514537, 2022). "The aberrations in methylation status within these regions were previously associated with changes in ESR1 and ESR2 transcriptional activity in estrogen-dependent cancers and endometriosis." (PMID 35682668, 2022). "It had 15 targets in the endometriosis-related gene set, and some of these targets, such as ESR1, ESR2 and PTGS2, had a high correlation score in MalaCards." (PMID 35130311, 2022). "In a baboon model of endometriosis, decreased ESR1 level was showed in endometrial stromal cells, while reduced ESR-2 expression was displayed in endometrial stromal and glandular epithelial cells." (PMID 36249421, 2022). "Increased expression levels of HSD3B2 gene and of ESR1 gene were demonstrated in endometrium of infertile women with endometriosis." (PMID 33153202, 2020). "In primary meta-analysis, they identified two SNPs at the locus rs71575922 in SYNE1 and rs1971256 in CCDC170, located in endometriosis up- and downstream of ESR1, respectively." (PMID 32370117, 2020). "In contrast, the ESR1 promoter is unmethylated in eutopic endometrium and heavily methylated in endometriosis, leading to lower ESR1 receptor levels in endometriotic vs. endometrial stromal cells." (PMID 32370117, 2020).
endometriosis (continued). "The rise in ESR1 in endometriosis corresponds to a decrease in αv/β3 integrin, which is an adhesion molecule normally expressed in the endometrium during the receptive window and putatively involved in successful implantation." (PMID 31387263, 2019). "ESR2 expression is unchanged in eutopic endometrium from women with endometriosis although one study reported increased ESR2/ESR1 ratio in endometriosis-affected endometrium." (PMID 31387263, 2019). "PGR and ESR1 are also found in the list of the common 39 genes from the three endometriosis-related data sets." (PMID 31879572, 2019). "Peritoneal fluid macrophages from women with endometriosis were shown to upregulate the expression of ESR1 and ESR2, and the expression of ESRs correlated with an increase in inflammatory cytokines." (PMID 31387263, 2019). "Our UL GWAS meta-analysis indicates that genes previously associated with endometriosis and involved in hormone-signaling pathways are also associated with UL (WNT4/CDC42, GREB1, ESR1, and FSHB)." (PMID 31649266, 2019). "ESR2, which is upregulated in OE, has been shown to suppress ESR1 expression in endometriosis by binding to the ESR1 promoter." (PMID 30728052, 2019). "Although there are contradicting results regarding ESR1 expression in ectopic endometrium, in particular ovarian endometriosis, it is widely accepted that the ESR1 gene has a pivotal role in endometriosis pathogenesis." (PMID 30487429, 2018). "Methylation of ESR1 frequently silences its expression in cancer, but our discovery of aberrant ESR1 methylation in endometriosis is novel." (PMID 24603652, 2014). "Two loci associated with both endometriosis and female infertility (WNT4 and ESR1) may share the same putative causal variant (PP >93.6%)." (PMID 40229599, 2025). "Whilst the polymorphism in estrogen receptor 1 (ESR1) may be associated with conditions characterized by abnormal ER (i.e., endometriosis), when assessed in the context of IVF outcomes for infertile women, SNPs in ESR1 provided limited predictive value." (PMID 39858500, 2025). "In women with endometriosis, normal endometrial function is compromised due to the up-regulation of estrogen signaling mediated through elevated levels of estrogen receptor alpha (ESR1) expression in secretory phase endometrium, compared to controls." (PMID 39200122, 2024). "Furthermore, aberrant ESR1 expression has been noted in individuals with endometriosis, where ESR1 transcript levels are reduced in women diagnosed with endometriosis when contrasted with those in the control group." (PMID 38910609, 2024). "Consistently, downregulation of ESR1 mRNA level in endometriosis was also reported in few studies." (PMID 38844959, 2024). "ESR1 might be involved in the initiation of endometriosis, while the overproduction of estradiol in endometriosis would drive ESR2 signaling to support endometriotic tissue survival and enhance inflammation." (PMID 38892003, 2024). "Despite the importance of ESR1 and estrogen signaling in endometriosis, the association of these three SNVs with endometriosis has not previously been investigated in detail." (PMID 39200122, 2024). "Two loci associated with both endometriosis and female infertility - WNT4 and ESR1 - may share the same putative causal variant (PP>93.6%, Supp." (PMID 38562841, 2024). "Given that endometriosis is an estrogen-dependent disease and clearly has a genetic background, we hypothesized that common SNVs functioning in ESR1 regulation in other hormone-dependent disease conditions are shared with endometriosis." (PMID 39200122, 2024). "However, in the endometrium of women with endometriosis, the regulation of ESR1 expression during the menstrual cycle seemed to be disturbed by a lack of significant downregulation of the receptor levels in the secretory phase endometrium." (PMID 39200122, 2024).
endometriosis (continued). "In addition, estrogen receptor 1 (ESR-1) levels are higher in the midsecretory phase endometrium of women with endometriosis-related infertility than in control subjects, although progesterone receptor expression levels are lower in these subjects." (PMID 38276248, 2024). "In our study, the AA genotype was neither associated with an increased endometriosis risk nor with the regulation of ESR1 expression in the endometrial tissue of young and leaner women with mild endometriosis." (PMID 39200122, 2024). "In contrast, polymorphisms in the estrogen receptor beta (ESR2) but not ESR1 gene are associated with stage IV endometriosis in Japanese women." (PMID 37676242, 2023). "ClusterB was revealed to be associated with significantly overexpressed VEGFA and VEGFC and, notably, downregulated ESR1 and PGR, which are characteristic biomarkers of endometriosis, indicating that clusterB might be highly linked to endometriosis." (PMID 36672827, 2022). "DNA methylation in ESR1 gene was significantly higher in endometriosis than in eutopic endometrium." (PMID 33153202, 2020). "Five additional new loci significantly associated with the risk of endometriosis (p < 5 × 10−8) of genes involved in sexual steroid hormone pathways (FN1, CCDC170, ESR1, SYNE1 and FSHB) were identified, for a total of 16 genomic regions associated with endometriosis risk in one or more populations." (PMID 32143537, 2020). "The objective of that study was to examine whether infertility, associated with endometriosis, may result from disturbed expression of HSD3B2, HSD17B1, HSD17B2, and ESR1/2 genes." (PMID 33153202, 2020). "ESR1 levels are reportedly increased in the secretory phase endometrium of women with endometriosis compared to controls, which may lead to increased estrogenic activity and proliferation, compromising normal uterine function." (PMID 31387263, 2019). "Additionally, the inhibitory action of PGR on ESR1 normally prevails in the endometrium during the window of receptivity, but women with endometriosis exhibit increased ESR1 through the mid-secretory phase, which encapsulates the implantation window in women." (PMID 31387263, 2019). "In addition to replicating previously reported loci, we identify five novel loci significantly associated with endometriosis risk (P<5 × 10−8), implicating genes involved in sex steroid hormone pathways (FN1, CCDC170, ESR1, SYNE1 and FSHB)." (PMID 28537267, 2017). "Genetic events in CDKN2A and ESR1 genes are rare in endometriosis." (PMID 24179489, 2013). "Microsatellites ESR1_TA and ESR2_CA in the ESR1 and ESR2 genes, respectively, have also been reported to be associated with other diseases such as bone mineral density, osteoarthritis, and endometriosis." (PMID 22792352, 2012). "The disruption of ESR2 and the ensuing decrease of the ESR1/ESR2 ratio could be the culprit for the cascade of molecular events that initiates cellular deregulation and tissue remodeling associated with endometriosis." (PMID 22203846, 2011). "We constructed three distinct m6A patterns, among which there was a subtype highly consistent with significant low expression of ESR1 and PGR, suggesting that the m6A pattern might be highly linked to endometriosis and could help to predict the occurrence of endometriosis and guide timely treatment." (PMID 36672827, 2022). "A rodent model of endometriosis revealed that treatment with candidate miRNA, let-7b resulted in a decrease in endometriotic lesion size and decreased expression of several genes important in the pathophysiology of endometriosis including Esr1, Esr2, CYP19a, and IL-6." (PMID 34244742, 2021). "Only rs12037376 (CDC42/WNT4), rs71575922 (SYNE1/ESR1), and rs77294520 (GREB1) associate with leiomyoma after correction for the number of tests (P < 0.05/19 = 2.6 × 10−3), with all three variants showing the same direction of effect for endometriosis and leiomyoma (logistic regression)." (PMID 30194396, 2018).
endometriosis (continued). "In addition to replicating 9 of the 11 previously reported European risk loci, this GWA meta-analysis identified 5 novel loci significantly associated with endometriosis risk (P<5 × 10−8), implicating genes involved in sex steroid hormone pathways (FN1, CCDC170, ESR1, SYNE1 and FSHB)." (PMID 28537267, 2017). "Higher levels of ESR1 (estrogen receptor 1) and ESR2 (estrogen receptor 2) in diabetic endometriosis tissues suggest a potential link between metabolic disturbances and hormonal signaling in disease progression." (PMID 40649777, 2025). "Endometriosis is an estrogen-dependent disease, with both ESR2 and ESR1 playing critical roles in its progression." (PMID 41054802, 2025). "ESR1 and ESR2 expression is upregulated in the eutopic and ectopic endometrium from endometriosis patients compared to control endometrium, with ectopic lesions showing higher expression of both genes compared to eutopic tissue." (PMID 40072055, 2025). "It is interesting to note that the endometrium of women with endometriosis has the abnormal expression of the B3-integrin subunit gene, which is a direct downstream target gene of both HOXA10 and ESR-1." (PMID 38276248, 2024). "Our study reported a crucial connection with protein targets such as SRC, ESR1, and PIK3 in endometriosis." (PMID 39598271, 2024). "This aberrantly low ESR1:ESR2 ratio changes the mode of action of estrogen and influences diverse pathological processes in endometriosis, including apoptosis, proliferation, invasiveness, and inflammation." (PMID 38549776, 2024). "In a study in Greece, women with endometriosis have a significantly higher frequency of a TC polymorphism recognized by the PvuII restriction enzyme and a fewer median number of microsatellite repeat polymorphisms in the estrogen receptor alpha (ESR1) gene than women without the disease." (PMID 37676242, 2023). "Previous studies have reported that the decreased ESR1/ESR2 in ectopic lesions leads to the decreased expression of PGR, which can exacerbate the inflammatory response, thereby contributing to endometriosis." (PMID 36860677, 2023). "The regulation of these genes, especially ESR1 and PGR, is known to induce estrogen-dependent inflammation and progesterone resistance in endometriosis patients." (PMID 36672827, 2022). "Deeper inquiry into endometrial epithelial-stromal crosstalk between ErbB2/ERK/ESR1 and PGR/MIG-6 signaling pathways will be of major importance to understanding infertility and endometriosis." (PMID 35232969, 2022). "ClusterB was demonstrated to be correlated with significantly overexpressed VEGF and notably downregulated ESR1 and PGR, which are convincing biomarkers of endometriosis." (PMID 36672827, 2022). "The results suggested that the bioactive compounds of WJD against endometriosis included 48 targeted genes, among which IL6 and ESR1 were closely related to inflammation and the endocrine system, respectively." (PMID 34257679, 2021). "The results of experimental study, concerning the analysis of ESR1, ESR2, PGR, and CYP19A1 genes, unveil the existence of certain correlations of their expression with endometriosis." (PMID 33153202, 2020). "The ESR1 and PGR expression levels were substantially lower, while the level of ESR2 gene expression was significantly higher in endometriosis than in normal endometrium." (PMID 33153202, 2020). "In parallel with the predecidua changes, various CEC types isolated from patients with endometriosis in our cohort showed different gene expression profiles, represented by typically elevated gene expression of KRT18, NANOG, and VIM or of KRT19 and ESR1." (PMID 31717910, 2019). "In fact, one study revealed that MPA can decrease ESR1 and ESR2 while increasing PR-A and PR-B in the endometrium women with endometriosis." (PMID 31387263, 2019). "There were several genes strongly expressed in endometriosis tissue: EPCAM, KRT18, WT1, MUC16, MUC1, and ESR1, if compared to the endometrial cells from healthy controls." (PMID 31717910, 2019).
endometriosis (continued). "Since E2′s effects are primarily enacted through ESR1 and ESR2, their expression levels are important in the assessment of E2 action in endometriosis." (PMID 31387263, 2019). "Additionally, functional validation of the isoform-specific signaling pathways, particularly the MAPK/PI3K/Akt activity in ESR1+ and ESR2+ stromal cells, are needed to determine their roles in endometriosis pathophysiology." (PMID 41000819, 2025). "Oestrogen also acts via specific receptors, oestrogen receptor-α (ESR1) and oestrogen receptor-β (ESR2), the latter of which has been demonstrated to be overexpressed in women with endometriosis and may play a role in disease development." (PMID 40628402, 2025). "This upregulation of ESR1 gene expression in women with endometriosis was observed only in women aged under 35 years and not in women aged over 35 years." (PMID 39200122, 2024). "This analysis showed that the increased ESR1 expression is seen in young women with endometriosis with rs2046210 GA but not with GG or AA genotypes." (PMID 39200122, 2024). "Indeed, in their research, differential methylation profiles in endometrial tissue of women with endometriosis were identified, involving genes like HOXA10, PR, and ESR1, which are crucial for normal reproductive function." (PMID 39311136, 2024). "In a previous report, we showed that Ki67, PGR-T, ESR1, and ESR2 constitute valid biomarkers for endometriosis progression since their levels and patterns of nuclear immunopositivity in ectopic lesions differed significantly from those of corresponding eutopic endometria or non-diseased endometria." (PMID 36788175, 2023). "The results illustrate that clusterB was correlated with a significantly lower expression of ESR1 and PGR and a higher expression of VEGF, which revealed that the cluster might have a correlation with endometriosis." (PMID 36672827, 2022). "A tendency of increased ESR1 expression was also seen in the endometrial tissues of young women with endometriosis compared to women without endometriosis in the proliferative (1.44-fold increase; adjp = 0.0508) and secretory (2.2-fold increase; adjp = 0.0584) menstrual cycle phases." (PMID 39200122, 2024). "The disease eutopic tissue’s lymphocyte cells comparison was not significant (OR = 0.994), showing that ESR1 and ESR2 are not co-expressed and tend to be uniquely and specifically expressed in endometriosis lymphocytes." (PMID 41000819, 2025). "Therapeutic agents targeting ESR1 are now under phase 3 clinical trials in endometriosis, and thus, we further performed attack analysis in the context of AKT1 + ESR1, with maximal network disconnection (~16%) achieved by 3-node removal." (PMID 35401535, 2022).